TERC (telomerase RNA component)
Diseases named in the same sentence as TERC in open-access papers (continued):
Sharing a sentence is not in itself a finding about the gene and the disease.
cancer (continued). "WS shares some common features with other telomere diseases, most represented by mutation of telomerase complex (TERC and TERT), like skin hyperpigmentation, premature hair greying, myeloid disorder, and risk of cancer." (PMID 26788395, 2015). "The upregulation of TERC, which is the RNA matrix for telomere synthesis, has been identified in several cancer entities and its effects on tumor growth include both telomerase activity-dependent and -independent pathways." (PMID 25596731, 2015). "Recently, increasing evidence suggests that telomere maintenance genes, such as TERT, TERC, TERF1, TERF2, TINF2, TERF2IP and POT1 are associated with cancer risk." (PMID 22970196, 2012). "The overexpression of TERC in cancer may be related to the lower degree of methylation of the TERC promoter, which also indicates the development of the disease." (PMID 39871386, 2025). "Inhibiting TERC is an area of active research and holds potential for therapeutic intervention as it is shown to effectively disrupt telomerase activity leading to telomere shortening in cancer cells." (PMID 39273409, 2024). "Genetic variants near TERT, TERC, or OBFC1 may have independent impact on the risk of certain types of cancer, which violates the exclusion restriction assumption of MR." (PMID 37232505, 2023). "In many eukaryotic cells, including stem cells and cancer cells, this loss is often counteracted by the expression of the telomerase reverse transcriptase (TERT) and its integral RNA template component hTR (encoded by TERC)." (PMID 35920280, 2022). "It has been proposed that elevated TERC expression could serve as a biomarker for cancer as its amplification has been detected in lung squamous cell carcinoma and esophageal squamous cell carcinoma." (PMID 33599797, 2021). "Similarly, knocking down TERC using siRNA leads to inhibition of cell proliferation and induction of apoptosis in cancer cells, as well as inhibition of xenograft tumor growth in nude mice." (PMID 33599797, 2021). "Both TERT and TERC play important roles in tumorigenesis and could be involved in various malignant tumours through telomere maintainance." (PMID 31988393, 2020). "Interestingly, two plasmids expressing the shRNA candidate with the strongest silencing effect toward either TERT or TERC (among three shRNA candidates for each target gene) showed similar cancer cell growth inhibitory effects." (PMID 31035374, 2019). "Thus, FXR1 is an important protein that regulates RNAs such as p21 and TERC to promote cancer progression." (PMID 27606879, 2016). "Variants in a gene cluster upstream-adjacent to TERC on human chromosome 3, which includes genes APRM, LRRC31, LRRC34 and MYNN, have been found to associate with telomere length, as well as related diseases, such as cancer and diabetes, in several human populations by multiple independent analyses." (PMID 34685603, 2021). "Unlike TERT, mutations in the TERC gene, or its promoter, are less prevalent in cancer." (PMID 33599797, 2021). "To test whether these two coordinated events such as down-regulation of p21 and up-regulation of TERC in cancer cells, independently or in combination to control senescence, we overexpressed p21 and silenced TERC by individual and combinatorial transfections in HNSCC cells." (PMID 27606879, 2016). "Genetic variation near TERT and TERC may influence cancer risk independent of its effect on telomere length, as telomerase has been shown to upregulate glycolysis and may contribute to the Warburg effect." (PMID 26646793, 2015). "LncRNAs such as TERC and TERRA regulate immortality by maintaining TL and preventing senescence in cancer cells." (PMID 39222177, 2025). "The dysregulation of TERC expression in oncogenesis may be attributable to different mechanisms, including aberrant alterations in transcriptional and epigenetic statuses, oncogenic signalling activation, gene amplification and among others, which depend on cancer types." (PMID 36394204, 2022).
cancer (continued). "Based on the 2^-(ddCt) for TERC/GAPDH and MYC/GAPDH from the controls in Group 2, the threshold of cancer detection for these markers was set at 3.12 and 0.155 respectively." (PMID 34790573, 2021). "To examine if this signature was LGG specific, we tested the correlation between the expression of signature genes (excluding TERT and TERC) and TERT in 32 cancer types." (PMID 33420056, 2021). "Cancer-related genes commonly amplified from 3q26 include PIK3CA, TBL1XR1, DCUN1D1, SOX2, MECOM, PRKCI, and TERC." (PMID 34436017, 2021). "Genomic profiling of ESCC tumors found 98% patients having amplification in one or more cancer‐relevant genes, as well as the co‐amplification of genes at adjacent chromosome locations, such as CCND1/FGF19 and TERC/SOX2/PIK3CA." (PMID 31851786, 2020). "As expected, TERC is constitutively expressed in all cells examined; whereas TERT is expressed in cancer cells (Hela, PANC1 and SUM15) and human induced pluripotent stem cells (iPSCs), but not in primary cells such as human aortic smooth muscle cells (HASMCs)." (PMID 31963842, 2020). "On the other hand, the telomere length-associated gene TERC and oxidative stress response gene NFE2L2 were more frequently amplified in the CHRNB4-high subgroup, which could immortalize cells and against oxidative stress for promoting cancer cell survival and escaping apoptosis." (PMID 32455963, 2020). "To demonstrate the importance of accurate lncRNA expression quantification, we investigated the expression profile of a number of well-known lncRNAs with important functions in cancer: HOTAIR, CDKN2B-AS1, TERC, LINC01106, and LINC01123." (PMID 31808800, 2019). "The TERT and TERC transcripts were highly expressed in A-549 and MDA-MB-231 cancer cells than in U87-MG cancer cells." (PMID 30460075, 2017). "Additional work is needed to warrant the recruitment of TERC by FXR1 and how this process controls telomere length in cancer." (PMID 27606879, 2016). "We have reported that MCAF1 is required for cancer cell proliferation by activating the transcription of the telomerase genes, TERT and TERC." (PMID 23935871, 2013). "While TERC knockdown does not significantly affect the viability of cancer cells, it sensitizes them to apoptosis induced by specific chemotherapeutic agents." (PMID 39871386, 2025). "Telomerase reactivation, a hallmark of cancer, not only maintains telomere length via its core components TERT and TERC, but also exerts non-canonical mitochondrial functions—reducing ROS, DNA damage, and apoptosis." (PMID 40492114, 2025). "TERC, the telomerase RNA, has been thought to be an unsuitable cancer marker because, unlike TERT mRNA, it is often expressed widely and occasionally even in the absence of telomerase activity." (PMID 40151802, 2025). "Several other non-polyadenylated transcripts, such as TERC (the RNA component of telomerase) and RMRP (an endoribonuclease implicated in cancer progression), were also highly differentially abundant in the rRNA- Dissociated samples." (PMID 37864274, 2023). "For telomerase negative cancers, termed alternative lengthening of telomeres (ALT) cancers, TERC is often detected, but TERT is lacking." (PMID 31294790, 2019). "Telomerase, a ribonucleoprotein complex containing an internal RNA component (TR or TERC) and a catalytic protein (TERT, Telomerase Reverse Transcriptase), enables telomere elongation; it is active in cancer cells and, transiently, in tissue in rapid proliferation." (PMID 30418933, 2018). "Telomere shortening could be induced in the cancer cells through downregulating the expression level of telomerase activity along with the decrease in TERT and TERC transcripts’ level." (PMID 30460075, 2017). "In contrast to TERT mRNA, telomerase RNA, TERC, is generally expressed ubiquitously, at times in the absence of telomerase activity, and thus it has been assumed that TERC would not be a suitable cancer marker." (PMID 27240403, 2016).
cancer (continued). "Although TERC expression is not tumour-specific its highly expressed level may be indicative of the presence of tumor in some cancer types." (PMID 40151802, 2025). "Similarly, we revealed that TERC promotes cellular inflammatory response by upregulating the expression of immune-related genes such as LIN37, TPRG1L, TYROBP and USP16 in human normal and cancer cells." (PMID 31294790, 2019). "Various lines of evidence have shown that the cancer-promoting activity of TERC seems to be independent of in vitro telomerase activity, consistent with the hypothesis that TERC might play a non-canonical role in DC pathogenesis." (PMID 27482813, 2016). "Unlike RNA interference therapeutics that directly suppress the expression of TERC or TERT to disrupt telomere maintenance and in cancer, hTERTC27 neither suppresses the expression levels of these genes nor restricts telomerase activity." (PMID 31035374, 2019). "The copy numbers of TERC and CLDN1 in cancer tissues were both increased significantly compared with normal cervical tissue." (PMID 27974683, 2016). "This regulation does not require the presence of TERC, suggesting that TERT–MYC interaction on MYC-regulated promoters are independent of telomerase activity and could also explain why TERT and MYC levels are highly correlated in cancer cells." (PMID 33599797, 2021).
tumor (50 papers, 2006 to 2025). "For example, TERC/CCL25 is associated with an increase in the proliferative potential of tumor cells." (PMID 36354566, 2022). "Here, we report two tumor samples where TERC template mutations were reflected in telomeric repeats." (PMID 36006930, 2022). "Here, we report on the rare occurrence of two tumor samples where TERC template mutations were reflected in telomeric repeats." (PMID 36006930, 2022). "Numerous studies have shown that telomerase activity is increased in a variety of tumor cells and that increased telomerase activity is associated with increased copy number of telomerase core members TERC and TERT genes." (PMID 33256840, 2020). "Gains of TERC gene significantly associate with a gradual increasing amplification pattern in tumour progression of ovarian malignancies." (PMID 29751586, 2018). "Moreover, this cluster tumor is associated with amplified TERC, TERT, MYC, CCND1, and BCL2L1." (PMID 34815793, 2021). "Upon knockout of the TERC gene, in vitro experiments demonstrate a reduction in tumor cell migratory capacity, accompanied by G1-phase cell cycle arrest." (PMID 39871386, 2025). "TERC lncRNA facilitates PCa cell metastasis, migration, proliferation, and migration by sponging the hsa-miR-320 family and inhibiting their tumour-suppressive abilities." (PMID 37754243, 2023). "In LncSEA, TERC was shown to be hypermethylated and to interact with four members of the miR-320 tumour-suppressor family, namely hsa-miR-320a, hsa-miR-320b, hsa-miR-320c, and hsa-miR-320d." (PMID 37754243, 2023). "The tumor formation rate and survival rate in mouse with dual inactivation of TERC and INK4a were higher than those in the control group, and re-expression of TERC can complement this phenotype." (PMID 38111043, 2023). "Two other tumour-suppressor miRNAs, hsa-miR-4429 and hsa-miR-338-3p, were also shown to interact with TERC." (PMID 37754243, 2023). "The LncSEA analysis revealed that TERC was hypermethylated and that it interacts with several miRNAs, especially tumour-suppressive miRNAs." (PMID 37754243, 2023). "We also observed that one of the four tumours from disease‐free patients with long follow‐ups and short telomeres showed elevated TERC expression and TERT copy gain." (PMID 35979662, 2022). "It should also be noted that the telomerase RNA component (TERC) gene is involved in the early stages of tumor formation." (PMID 35892421, 2022). "The three pH-LAMP tests (hTERT mRNA, MYC mRNA and TERC DNA) each had poor sensitivity but excellent specificity for predicting the presence of residual tumor." (PMID 34790573, 2021). "Thresholds for tumor marker detection for Group1 were set from Group2 analysis (any hTERT, TERC/GAPDH 3.12, MYC/GAPDH 0.155)." (PMID 34790573, 2021). "The expression of TERT and TERC in normal cells is small, but the expression of TERT and TERC in tumor cells is indeed very substantial." (PMID 33869033, 2021). "Both amplifications were reported to be genetic alterations that induce strong TERT and TERC overexpression in some tumours, although the specificity of these amplifications remains to be established." (PMID 29751586, 2018). "This wide data collection enabled us to portray, by organ/system and histotypes, the prevalence of TERTp mutations, TERT and TERC amplifications, and ALT in human tumours." (PMID 29751586, 2018). "RTEL, TERC and TRF1 showed significantly different methylation between tumor and normal tissues with hyper-methylation of RTEL, TERC in tumor in TCGA data set." (PMID 28424414, 2017). "So, although the TERT/TERC/dyskerin complex in tumour cells is accepted as the leader form, pontin and reptin gene expressions must also be expected to increase." (PMID 28443573, 2017).
tumor (continued). "Next, we tested the RNA levels of TERC in eight tumor tissue samples compared to normal adjacent tissues." (PMID 27606879, 2016). "Our analyses indicate that TERC is overexpressed in HNSCC tumor tissues compared to normal adjacent tissues." (PMID 27606879, 2016). "The over- representation of polyploidy and/or TERC/SOX2 amplification in tumor samples was statistically significant compared to controls (p = 0.01)." (PMID 24410919, 2014). "The over representation of polyploidy and/or TERC/SOX2 amplification in tumour samples was statistically significant when compared to controls (p = 0.01)." (PMID 24410919, 2014). "Recognized tumor genes, such as EVI1 and MDS1, and genes associated previously with CC (TERC, TNFSF10, and PIK3CA) are located in this region." (PMID 22412903, 2012). "The absolute mean number of TERC signals per nuclei ranged between 2.3 (case 11) and 5.2 (case 10), and in five of the tumours nuclei with more than 10 signals were repeatedly encountered." (PMID 16847471, 2006). "We observed high proportions of nuclei with increased absolute copy numbers for TERC in all tumours (mean 3.3; range 2.3–5.2)." (PMID 16847471, 2006). "TERC is an essential component of TERT's tumor promoting effect." (PMID 39871386, 2025). "This overexpressed TERC fosters proliferation of tumor cells and promotes tumor growth." (PMID 39871386, 2025). "We confirmed that there was higher expression of TERT and TERC in the HT1080-LT xenograft tumours." (PMID 39728924, 2024). "TERC is reportedly overexpressed in various tumours including PCa." (PMID 37754243, 2023). "Notably, TERC lncRNA was shown to interact with tumour-suppressor miRNAs hsa-miR-4429 and hsa-miR-320b." (PMID 37754243, 2023). "Along with the understanding that lncRNAs may function as ceRNAs sponging miRNAs, it can be concluded that TERC may be an oncogenic lncRNA, which sponges tumour-suppressive miRNAs to promote PCa progression." (PMID 37754243, 2023). "As many PTC tumours lack TERT expression or promoter mutations, it will be interesting to evaluate whether TERC can serve as a prognostic factor in those PTC patients." (PMID 36394204, 2022). "In order to demonstrate the role of RPL22, Kheimar and Kaufer deleted TERC from MDV, thus abolishing tumorigenesis, and showed that its substitution with EBER-2 (Epstein-Barr virus-encoded RNA 2) restored tumour formation in MDV that lacked TERC." (PMID 36499514, 2022). "The combined evidence from all the TERC studies reviewed suggests an oncogenic role for TERC whereby dysregulation of its expression could promote tumor development." (PMID 33599797, 2021). "Therefore, one would predict that loss-of-function mutations in TERT or TERC would inhibit tumorigenesis, while overexpression of TERT would promote tumor formation." (PMID 34439356, 2021). "In this review, we address seven different TMMs in tumour cells: mutations of the TERT promoter (TERTp), amplification of the genes TERT and TERC, polymorphic variants of the TERT gene and of its promoter, rearrangements of the TERT gene, epigenetic changes, ALT, and non-defined TMM (NDTMM)." (PMID 29751586, 2018). "Below, we present the prevalence of TERT and TERC amplifications in several tumour types." (PMID 29751586, 2018). "Compared to normal, TERC DNA is amplified in multiple loci of the tumor tissue samples." (PMID 27606879, 2016). "The intra and inter-tumor heterogeneity for the amplification of TERC/SOX2 locus was observed." (PMID 24410919, 2014). "In addition, the RNA component of the telomerase (TERC) was expressed at very low level in this tumour as compared with the tumours of the control set." (PMID 21170331, 2010). "Interestingly, loss of p21 in TERC -null mice with dysfunctional telomeres leads to improved stem cell function and increased lifespan without accelerating tumor formation." (PMID 27606879, 2016).